CD44 (CD44 molecule (IN blood group))
Diseases named in the same sentence as CD44 in open-access papers (continued):
Sharing a sentence is not in itself a finding about the gene and the disease.
Insulin resistance (38 papers, 2011 to 2025). Increased resistance towards insulin, that is, diminished effectiveness of insulin in reducing blood glucose levels. "For instance, CD44, implicated in insulin resistance, has been studied as a therapeutic target with potential for T2DM." (PMID 39281650, 2024). "CD44's role in adipose tissue inflammation, particularly diet induced, and its association with insulin resistance and T2DM has been established previously." (PMID 39281650, 2024). "CD44 is also linked to Type 2 diabetes and insulin resistance in patients through regulating adipose tissue inflammation which will be discussed later." (PMID 37383542, 2023). "Increased expression of CD44 in adipose tissue is shown to be associated with inflammation and insulin resistance in patients with Type 2 diabetes, which is consistent with in vivo evidence." (PMID 37383542, 2023). "Osteopontin, e-selectin and hyaluronic acid are the main ligands of CD44, and human adipose tissue CD44 is associated with localized inflammation and systemic insulin resistance." (PMID 34899679, 2021). "Adipose tissue inflammation and insulin resistance associate with high CD44 expression, while weight loss reduces the expression of CD44 and the amount of macrophages in adipose tissue." (PMID 31720917, 2020). "CD44 plays a causative role in the development of adipose tissue inflammation and insulin resistance in mice and has been related to type 2 diabetes in humans." (PMID 24871103, 2014). "While this manuscript was in preparation, an expression-based genome-wide association (eGWAS) study linked CD44 to type 2 diabetes in humans and reported that CD44-deficiency ameliorates insulin resistance in mice and humans." (PMID 23505504, 2013). "Consistent with this, both HA and its receptor CD44 are implicated in insulin resistance." (PMID 39451245, 2024). "In humans, both HA and its receptor CD44 are implicated in insulin resistance and glycemic control." (PMID 39451245, 2024). "In addition, CD44 is responsible for insulin-resistance in adipose tissue, as CD44 deficiency reduces insulin-resistance while increasing lipid accumulation in mouse and human white fat tissue." (PMID 36735684, 2023). "Additionally, it was shown that CD44+ likely plays a causative role in the development of adipose tissue inflammation and insulin resistance in rodents and humans." (PMID 28053691, 2016). "In summary, our study demonstrates that mice deficient in CD44 are considerably resistant to diet-induced hepatic steatosis, fibrogenesis, and inflammation, adipose-associated infiltration of M1 macrophages, glucose intolerance, and insulin resistance." (PMID 23505504, 2013). "Moreover, CD44 is strongly associated with adipose tissue insulin resistance." (PMID 37383542, 2023). "Given that Cd44 is downregulated, the role of insulin resistance is decreased, and lipid metabolism is increased, this indicates that the metabolic pathway effects of NMES are consistent in whole-brain tissue and muscle tissue in WT conditions." (PMID 40869172, 2025). "In humans, serum CD44 levels are positively correlated with insulin resistance and glycemic control." (PMID 39451245, 2024). "Ablation of CD44 by genetic deletion or anti-CD44 monoclonal antibody administration reduced adipose tissue immune cell infiltration and insulin resistance in diet-induced obese mice." (PMID 38692289, 2024). "Genetic deletion of CD44 also ameliorates HFD-induced skeletal muscle insulin resistance in obese mice." (PMID 38692289, 2024). "CD44 has been shown to promote inflammation and insulin resistance, which are vital components of metabolic syndrome." (PMID 38809924, 2024). "Pharmacologic and genetic studies suggest that hyaluronan and its receptor CD44 play a role in the aetiology of skeletal muscle insulin resistance in vivo." (PMID 37383542, 2023).
Insulin resistance (continued). "Increased ECM deposition contributes to the pathogenesis of insulin resistance at least in part through the activation of cell surface integrin receptors and CD44 signalling cascades." (PMID 37383542, 2023). "It has been shown that CD44 is elevated in diabetic tissues, which is also consistent with our analysis, and CD44 is correlated with insulin resistance and glycaemic control levels." (PMID 37904700, 2023). "In a high-fat diet (HFD) mouse model, IM7 (an anti-CD44 monoclonal antibody) injection suppressed fasting blood glucose levels, weight gain, liver steatosis, and insulin resistance, even superior to metformin and pioglitazone." (PMID 36845555, 2023). "For example, a gene expression-based GWAS in both mice and humans found that CD44 likely plays a critical role in the development of adipose tissue inflammation and insulin resistance, and obese mice have increased adipose expression of CD44." (PMID 35410390, 2022). "This is supported by the observation that CD44-deficient mice exhibit reduced susceptibility to HFD-induced AT macrophage infiltration, AT inflammation, and insulin resistance." (PMID 35406450, 2022). "In agreement with this, genetic blockade of CD44 improved insulin resistance by suppressing adipose tissue inflammation in DIO mice, leading to normalized fasting plasma glucose level and macrophage infiltration into adipose tissue in DIO mice." (PMID 33003609, 2020). "CD8+CD44+CD153+ T cells from the mice fed a HFD exacerbated insulin resistance than those from the mice fed a NCD." (PMID 30867412, 2019). "It was recently demonstrated that CD44+ is overexpressed in inflammatory cells in obese patients adipose tissue and serum CD44+ cells level is positively correlated with insulin resistance and glycemic control." (PMID 28053691, 2016). "Likewise, genetic deletion of CD44 ameliorates diet-induced skeletal muscle insulin resistance accompanied by improved muscle vascularization." (PMID 37383542, 2023). "Thus, CD44 renders a biomarker for insulin resistance and a possible therapeutic target for T2D treatment." (PMID 37614712, 2023). "In addition, treatment of obese mice with anti‐CD44 monoclonal antibody reduced fasting glucose levels, hepatic steatosis and insulin resistance to the level of treatment with metformin and pioglitazone." (PMID 37904700, 2023). "Moreover, in humans, CD44 was overexpressed in inflammatory cells in obese adipose tissue, and its serum level was positively correlated with insulin resistance and glycemic control." (PMID 33003609, 2020). "Importantly, treatment with anti-CD44 antibody improved insulin resistance, adipose inflammation, hepatic steatosis and weight gain in diet induced obese mice, reflecting the potential impact of modulating T cell receptors on the outcome of metabolic diseases." (PMID 30949049, 2019). "Interestingly, we have observed an increased expression of the CD44 surface marker, which is strongly correlated with inflammation, insulin resistance, and type 2 diabetes." (PMID 29977307, 2018). "Moreover, it was demonstrated that the application of the CD44 monoclonal antibody protected mice fed with a high-fat diet against insulin resistance, liver steatosis, and hyperglicemia." (PMID 29977307, 2018). "Our study indicates that CD44 plays a critical role in regulating several aspects of metabolic syndrome and may provide a new therapeutic target in the management of insulin resistance." (PMID 23505504, 2013). "Our study demonstrates that CD44-deficient mice (CD44KO) exhibit a significantly reduced susceptibility to the development of high fat-diet (HFD)-induced hepatic steatosis, WAT-associated inflammation, and insulin resistance." (PMID 23505504, 2013). "The exact role of CD44 and RHAMM in regulating cardiac function and insulin resistance merit further investigations." (PMID 38908792, 2024).
Insulin resistance (continued). "High fat diet feeding in mice increases CD44 protein expression in muscle, and mice lacking CD44 gene have increased muscle vascularization and ameliorate diet-induced insulin resistance in skeletal muscle." (PMID 37383542, 2023). "Interestingly, these findings agree with studies that reveal that interaction between CD44 and OPN represents a crucial ligand-receptor pair that facilitates systemic insulin resistance." (PMID 33047155, 2020).
myeloma (37 papers, 2009 to 2026). "G-CSF treatment both in healthy individuals and myeloma patients caused increased levels of circulating neutrophils that express the osteopontin receptor CD44." (PMID 27447610, 2016). "Here, we show that a novel pan-HDACi AR-42 downregulates CD44, a glycoprotein that has been associated with lenalidomide and dexamethasone resistance in myeloma both in vitro and in vivo." (PMID 26429859, 2015). "Like the myeloma-derived CD44-HABDs, the partial monosialo glycoform also displays a large number of contacts between the glycans N100 and N110 (Note SD)." (PMID 33664400, 2021). "And other study identified that SPP1 stimulated multiple myeloma cell proliferation through binding to CD44 and was involved in migration through binding to CD44 or αvβ3." (PMID 32843960, 2020). "CD44 has played a particularly important role in malignant cell interaction with the BMN in myeloid malignancies such as multiple myeloma, CML or AML." (PMID 32796596, 2020). "Expression of adhesion molecules VLA4, LFA1, and CD44 have been shown to correlate with increased angiogenesis in active myeloma." (PMID 33634031, 2020). "As a receptor of hyaluronic acid (HA), CD44 confers resistance to lenalidomide in myeloma cells as the factor that CD44/HA adhered to BMSCs more strongly in lenalidomide-resistant MM cells, suggesting CD44 and BMSC-mediated CAM-DR." (PMID 30405034, 2018). "Among these missing proteins were the cell adhesion molecules CD44 and α4β1 integrin, which we have shown to play roles in myeloma cell adhesion." (PMID 29088739, 2017). "Interestingly, CD44 has been shown to be a key player in drug resistance of other hematological malignancies such as multiple myeloma." (PMID 39796762, 2025). "The myeloma cells express adhesion molecules on their cell membrane which can bind with the components of the extracellular matrix, like fibrinogen & laminin bind to β1-integrins, hyaluron with CD44 and collagen-I binds to syndecan (CD138)." (PMID 40296907, 2025). "In addition to the α4β1-VCAM-1 interaction, the other significant players in myeloma cell trafficking are α4β7 integrin which interacts with MAdCAM-1 and CD44 which interacts with fibronectin." (PMID 40296907, 2025). "Overexpression of CD44 has been observed in lenalidomide-resistant human multiple myeloma cell lines (HMCLs), with increased adhesion to bone marrow (BM) stromal cells, while inhibition of CD44 reduced the adhesion of multiple myeloma cells and reversed the resistance to lenalidomide." (PMID 33968932, 2021). "In addition we have also shown that myeloma-derived serglycin can bind to CD44." (PMID 29088739, 2017). "Hence, we can speculate that the downregulation of CD44 expression upon pan-HDACi treatment has the potential to sensitize to therapy myeloma CSC in the bone marrow niche, a hypothesis that needs further evaluation." (PMID 26429859, 2015). "Thus, our findings shed light on potential novel combinatorial therapeutic approaches modulating CD44 expression, which may help overcome lenalidomide resistance in myeloma patients." (PMID 26429859, 2015). "In eight of these, we examined 12 surface markers commonly used in myeloma research, while in four cases we studied only a subset of them (CD38, CD44, CD45, CD49d, CD69, CD86, CD138, and CD184)." (PMID 39493694, 2024). "RNA-sequencing analysis suggested communication between RUNX2, M-CSF, ITGB3, CD44, LCN2, and CLU in RUNX2 k/in myeloma cells." (PMID 36897488, 2023). "IL-15 mDCs also showed higher stimulatory capacity regarding autologous T cells, a higher proportion of CD44+ and IFN-γ+ in CD4+ and CD8+ T cells, and higher cytotoxicity of T cells against cancer cell lines and patient autologous primary myeloma cells." (PMID 35413499, 2022). "MTI-101 is a first-in-class peptidomimetic that binds a CD44/ITGA4 containing complex and triggers necrotic cell death in multiple myeloma cell lines." (PMID 28578393, 2017).
myeloma (continued). "Experimental models further confirm that the absence of CD44 weakens tumor-endothelial adhesion and reduces invasiveness, though not affecting proliferation, while injection of CD44-positive cells promotes bone metastasis and myeloma-like lesions in vivo." (PMID 41596432, 2026). "Notably, IL-15 mDCs showed very good stimulatory capacity for autologous CIK cells, a higher proportion of CD44+, IFN-γ+, granzyme B+, and NKG2D in CIK cells, and a higher cytotoxicity of CIK cells against cancer cell lines and patient autologous primary myeloma cells." (PMID 35413499, 2022). "However, reduced expression of cell adhesion molecules like VLA-4, CD44, P-selectin, and CD56, promotion of homing of myeloma cells by decreased expression of chemokine receptors like CCR1, CCR2, and CXCR4, and increased angiogenesis have been proposed as mechanisms." (PMID 31467739, 2019). "Interestingly, in that study T567D ezrin induced capping of CD44, but not uropod formation in a naturally unpolarized myeloma cell line, indicating that in these cells the machinery for uropod formation is lacking, in contrast to the T cells used in our study." (PMID 23579783, 2013). "Earlier, lack of CD44-expression in EBV-positive or EBV-negative BL cell lines, up-regulation of serglycin and CD44 in EBV+ BL cells, down-regulation of syndecan-1/CD138 in EBV-infected multiple myeloma cells and fibronectin and collagen in multiple myeloma patients have already been reported." (PMID 26527314, 2015).
endometriosis (35 papers, 2010 to 2026). The growth of functional endometrial tissue in anatomic sites outside the uterine body. "Tunicamycin inhibited the N-linked glycosylation of CD44, thus inhibiting the adhesion of endometrial cells to peritoneal mesothelial cells, suggesting a role in the establishment of early endometriosis lesions." (PMID 39062484, 2024). "In the context of endometriosis, CD44 expressed by ectopic endometrial cells is linked to aberrant cell adhesion." (PMID 33807420, 2021). "CD44, a cell surface glycoprotein involved in cell adhesion and migration, has emerged as a promising focus for research seeking to understand the complex mechanism underlying endometriosis." (PMID 37509675, 2023). "This study suggests that BBP exposure may affect the survival rate of endometriotic lesions and that this effect is associated with elevated expression of CD44 on pDCs in the context of endometriosis." (PMID 33807420, 2021). "B-GalNAc inhibits the O-linked glycosylation of CD44, thus significantly inhibiting the adhesion of endometrial cells to peritoneal mesothelial cells, suggesting that the O-linked glycosylation of CD44 plays a role in the establishment of early endometriosis lesions." (PMID 39062484, 2024). "Due to its pluripotency and its relation to endometriosis, CD44 expression has been studied in endometrial carcinomas." (PMID 40422510, 2025). "Other supplementation studies have shown positive effects of increased vitamin D on specific disease markers for endometriosis such as β‐catenin activity and the cluster designation (CD) endometrial marker CD44." (PMID 39739404, 2025). "Vitamin D supplementation (50,000 IU/week, 12–14 weeks) reduced CD44 expression (CD44 is upregulated in endometriosis)." (PMID 39739404, 2025). "At baseline the authors showed that expression of the lymphocyte/endometriosis marker CD44 was elevated in serum, peritoneal fluid and endometrial tissue from women with endometriosis compared to healthy controls." (PMID 39739404, 2025). "Different biomarkers were sought, and the researchers found that the concentration of soluble CD44 in the sera and endometrial fluid of endometriosis patients was higher than that of healthy women." (PMID 39684461, 2024). "In a murine model of endometriosis, the role of epigenetic regulation of the Wnt/β-catenin/CD44 signaling pathway was found to be important in the invasion and migration of endometrial epithelial cells in ectopic tissue." (PMID 39684461, 2024). "CD44 was previously shown to be elevated in the eutopic endometrium of patients with endometriosis and is involved in the attachment and invasion of endometrial cells into the peritoneum." (PMID 38402336, 2024). "It seems that in the normally located endometrial tissue of endometriosis-affected patients, CD44 has an up-regulated turnover." (PMID 37509675, 2023). "More research in this field is needed to determine the precise association between endometriosis and the serum and tissue levels of OPN and CD44 expression." (PMID 37509675, 2023). "In endometriosis specimens, reduced CD44 tissue levels indicate a quantifiable therapeutic response." (PMID 37509675, 2023). "Despite the fact that CD44 was substantially expressed in every case of endometriosis, a positive score was discovered in 32 (60%) of the untreated cases and 21 (40%) of the treated cases." (PMID 37509675, 2023). "We evaluated the immunoreactivity of the epithelial and stromal components in the endometriotic tissue to determine if CD44 and OPN expression levels were implicated in the progression of endometriosis (i.e., the extension of lesion fibrosis in endometriosis)." (PMID 37509675, 2023). "The concentration of soluble CD44 in the serum and endometrial fluid of endometriosis patients was higher than that of healthy women." (PMID 36612107, 2022). "The eutopic endometrium of women with endometriosis in the mid-secretory phase expressed significantly higher levels of CD44+ cells including CD44v6 molecules." (PMID 36612107, 2022).